ACSL4 (acyl-CoA synthetase long chain family member 4)
Diseases named in the same sentence as ACSL4 in open-access papers (continued):
Sharing a sentence is not in itself a finding about the gene and the disease.
acute kidney injury (23 papers, 2017 to 2025). Sudden and sustained deterioration of the kidney function characterized by decreased glomerular filtration rate, increased serum creatinine or oliguria. "Dysregulation of ACSL4 is associated with multiple diseases, including cancer, neurodegenerative disorders, cardiovascular diseases, acute kidney injury, and metabolic syndromes." (PMID 40395328, 2025). "Dysregulation of ACSL4 is linked to a variety of diseases, including cancer, neurodegenerative disorders, cardiovascular disease, acute kidney injury, and metabolic disorders (such as obesity and non-alcoholic fatty liver disease)." (PMID 37372148, 2023). "Cdh16Cre-ACSL4F/F mice were obtained after knocking out the ACSL4 gene in the renal tubules of mice with acute renal failure, and ACSL4 knockout mice had a significant reductions in ferroptosis and some improvements in the pathological damage associated with renal failure." (PMID 38590315, 2024). "Ferroptosis also occurs in the course of acute kidney injury (AKI), which influences kidney inflammation, and the main cause of ferroptosis in AKI is ACSL4." (PMID 40872573, 2025). "XJB-5-131 has a high affinity for TECs and reduces I/R-induced renal injury in mice by downregulating the expression of ACSL4 to inhibit ferroptosis. miR-20a-5p is significantly upregulated in kidney transplantation patients and mice with acute kidney injury." (PMID 39396974, 2024). "Rosiglitazone can reduce the level of arachidonic acid, similar to the level of ACSL4 knockout cells, and also improve the survival rate of Gpx4 knockout mice to avoid renal failure death." (PMID 39872050, 2024). "In previous studies, ACSL4 has been shown to be involved in a variety of diseases such as rectal cancer, bladder cancer, chronic obstructive pulmonary disease, acute kidney injury, and non-alcoholic steatohepatitis through the ferroptosis pathway." (PMID 38127902, 2023). "Some scholars have found that ACSL4 promotes ferroptosis and is highly expressed in renal tissues in acute kidney injury (AKI)." (PMID 38161691, 2023). "One study showed that acyl-CoA synthetase long-chain family member 4 (Acsl4) is a predictive and pharmacodynamic biomarker of ferroptosis in vivo in acute kidney failure." (PMID 34426760, 2021). "The role of ACSL4 and ferroptosis upon endoplasmic-reticulum (ER)-stress-induced acute kidney injury (AKI) is unknown." (PMID 38799564, 2024). "Alterations in ACSL4′s activity and expression contribute to the development and progression of various diseases, such as obesity, acute kidney injury (AKI), neurodegenerative diseases, cardiovascular diseases, exertional heat stroke, non-alcoholic fatty liver disease (NAFLD), and cancer." (PMID 37372148, 2023). "Here, we have found that ACSL4 is both a predictive biomarker and pharmacodynamic marker of the regulated cell death modality of ferroptosis in vivo in acute kidney failure, thereby providing an important platform for clinical monitoring and diagnosis of ferroptosis-mediated pathologies." (PMID 28551825, 2017). "Recently, miR-20a-5p negatively regulates ACSL20 by targeting the 5`untranslated region of mRNA, thereby inhibiting ACSL4-dependent ferroptosis and attenuating acute kidney injury (AKI) triggered by renal ischemia-reperfusion injury." (PMID 37058073, 2023). "In IRI-induced acute kidney injury (AKI), H/R induces the ferroptosis of human proximal tubular epithelial cells (HK-2) through upregulating ACSL4 and COX-2, as well as down-regulating GPX4 and FTH1 in the kidney tissues." (PMID 37048123, 2023). "In the study of acute kidney injury (AKI) and intestine IRI, ACSL4 was induced during IRI." (PMID 38065978, 2023). "Kinetic studies in different cultured cell lines, and models of acute renal failure in mice and humans, demonstrated that ACSL4 was initially upregulated in non-fatal ferroptosis, thereby uncovering this molecule as the first reliable protein biomarker for the detection of this cell death modality." (PMID 28551825, 2017).
Cerebral ischemia (23 papers, 2019 to 2025). Restriction of arterial blood supply to the brain associated with insufficient oxygenation to support the metabolic requirements of the tissue. "Conversely, the risk of cerebral ischemia was observed to increase with the overexpression of ACSL4." (PMID 37351420, 2023). "Furthermore, studies have shown that calycosin mitigates damage caused by brain ischemia/reperfusion by suppressing ACSL4-mediated ferroptosis." (PMID 40191596, 2025). "A study demonstrated that in a focal cerebral ischemia mice model, ACSL4 promotes neuronal death by facilitating neuronal ferroptosis." (PMID 40365351, 2025). "Subsequently, we employed Western blot analysis and discerned remarkable shifts in GPX4, ACSL4, and TfR expressions within peri‐infarct cortical and hippocampal areas post‐cerebral ischemia." (PMID 40376919, 2025). "Knocking out ACSL4 alleviated ischemic brain injury, whereas overexpression of ACSL4 exacerbated cerebral ischemia." (PMID 40365351, 2025). "Tongqiao Huoxue Decoction (TQHX) confers neuroprotection against cerebral ischemia–reperfusion injury by promoting the ubiquitin-dependent degradation of ACSL4." (PMID 41306421, 2025). "Recent studies have found that calycosin inhibited tMCAO/R or OGD/R-induced ACSL4 upregulation and promoted the recovery of neural function after cerebral ischemia in rats." (PMID 38393376, 2024). "Berberine suppresses cerebral ischemia–reperfusion-injury-induced ferroptosis by downregulating ACSL4 and upregulating SLC7A11 expression." (PMID 38892270, 2024). "For example, baicalein suppresses ferroptosis to decrease cerebral ischemia–reperfusion injury by downregulating the ferroptosis-inducing ACSL4 gene and upregulating ferroptosis-inhibiting genes (GPX4 and SLC7A11) in brain tissues." (PMID 38892270, 2024). "In the cerebral ischemia/reperfusion model, ACSL4 knockdown attenuates ischemic brain injury while ACSL4 overexpression exacerbates ischemic brain injury." (PMID 37373168, 2023). "Thrombin stimulates ferroptosis signaling by promoting the mobilization and subsequent esterification of arachidonic acid via ACSL4 during cerebral ischemia/reperfusion." (PMID 37372148, 2023). "Pomelo peel essential oil (PPEO) also has a neuroprotective effect after cerebral ischemia/reperfusion injury by inhibiting the expression of ACSL4 and ferroptosis." (PMID 36507355, 2022). "In vitro model of cerebral ischemia, increases in acyl-coa synthetase long-chain family member 4 (ACSL4) and 12/15-lipoxygenase (12/15-LOX) have been shown to increase polyunsaturated fatty acids (PUFAs) such as arachidonic acid (AA) and adrenal acid (AdA)." (PMID 36210857, 2022). "The inhibition of ACSL4 prevented brain ischemia in mice, while the upregulation of ACSL4 deteriorated ischemic brain injury resulting from ferroptosis." (PMID 35401208, 2022). "Redox-responsive transcription factor sp1, which is dysregulated in AD and cerebral ischemia, reportedly upregulates the expression of ACSL4 by directly binding to the ACSL4 regulatory region." (PMID 34689160, 2021). "In summary, the upregulation of ACSL4 after cerebral ischemia induces ferroptosis in neurons, leading to IS injury." (PMID 32848555, 2020). "Studies have shown that ACSL4 is widely expressed in the brain tissue, especially in the CA1 region of the hippocampus, and the expression of ACSL4 increases gradually during cerebral ischemia." (PMID 31447633, 2019). "For instance, thrombin induces ACSL4-dependent ferroptosis during cerebral ischemia/reperfusion." (PMID 37372148, 2023). "Moreover, knockdown of ACSL4 protected mice against brain ischemia and neuroinflammation, whereas, forced overexpression of ACSL4 reportedly exacerbated ischemic brain injury." (PMID 35510808, 2022). "Meanwhile, we sought to examine the efficacy of ACSL4 on modulating ferroptosis in a cerebral ischemia model and focused on whether inhibition of ACSL4 facilitated neurological recovery in an anti-ferroptosis manner." (PMID 33889074, 2021).
Cerebral ischemia (continued). "Additionally, ACSL4 is widely expressed in brain tissues and is increased during cerebral ischemia, with an increased expression of miRNA-347 upregulating ACSL4 at the post-transcriptional level, and mediating neuronal death." (PMID 32848555, 2020). "However, the relationship between cerebral ischemia and ACSL4 expression cannot be generalized." (PMID 38393376, 2024). "It has been used as a potential target regulated by miR-347 during cerebral ischemia, and its mechanism of action may be the overexpression of miR-347 after cerebral ischemia; this then indirectly regulates ACSL4 through transcription to mediate neuronal ferroptosis." (PMID 35481263, 2022). "Piceatannol protects against cerebral ischemia or reperfusion injury by inhibiting neuronal ferroptosis through the USP14/GPX4 axis, and ACSL4 in microglia fuels neuroinflammation." (PMID 41306421, 2025). "ACSL4 is widely expressed in brain tissue, especially in the hippocampal CA1 region, and the expression of ACSL4 is gradually increased during cerebral ischemia." (PMID 36385946, 2022).
Stroke (23 papers, 2021 to 2025). Sudden impairment of blood flow to a part of the brain due to occlusion or rupture of an artery to the brain. "miR-347 has been implicated in ACSL4 regulation, with elevated miR-347 levels observed in stroke patients correlating with increased ACSL4 expression." (PMID 41425599, 2025). "Inhibition of ACSL4 such as thiazolidinediones and rosiglitazone facilitates neurological recovery by regulation of ferroptosis after stroke and TBI." (PMID 40766185, 2025). "The results show that, compared to the model group, acupuncture significantly reduces the levels of ACSL4 in brain tissue after stroke, thereby inhibiting ferroptosis." (PMID 40842100, 2025). "This modulation is specifically characterized by the upregulation of GPX4 and downregulation of ACSL4 within ischemic penumbra tissues in mice post‐stroke." (PMID 40376919, 2025). "The meta‐analysis of five studies involving 270 rats evaluated the ferroptosis marker ACSL4 in brain tissue post‐stroke." (PMID 40842100, 2025). "Recent studies have also demonstrated that inhibiting ACSL4 can promote the recovery of neurological function after stroke by suppressing ferroptosis." (PMID 36995819, 2023). "Although ACSL4 is an important factor in ferroptosis after stroke, the research in this field remains limited." (PMID 35481263, 2022). "The increase of ACSL4 expression is frequently observed in the stroke models simulating ischemia/reperfusion neuronal injury." (PMID 36507355, 2022). "Down-regulation of acyl-CoA synthetase long-chain family member 4 (ACSL4) alleviates oxidative stress to suppress stroke-induced ferroptosis and recover neurological function." (PMID 36139919, 2022). "Inhibition of ferroptosis response can reduce stroke injury, and its mechanism is related to excitement related to iron overload, ACSL4 protein, 12/15-LOX expression, XCT expression, and increased sexual toxicity." (PMID 34413966, 2021). "This study indicates that inhibiting ACSL4 can promote the recovery of neurological function after stroke by suppression of ferroptosis." (PMID 33889074, 2021). "Moreover, we unveil a consistent elevation in ACSL4 and TfR expressions, along with the concentration of iron ions during the post‐stroke recovery phase." (PMID 40376919, 2025). "Notably, the signature molecule of ferroptosis, Acyl-CoA synthetase long-chain family member 4 (ACSL4), which regulates polyunsaturated fatty acids, has been implicated in enhancing the release of inflammatory factors in microglia during stroke." (PMID 38671843, 2024). "Inhibition of ACSL4 expression reduces lipid peroxidation and attenuates brain damage after stroke." (PMID 36967397, 2023). "This study demonstrated that inhibition of ACSL4 could promote recovery of neurological function after stroke by inhibiting ferroptosis." (PMID 37373168, 2023). "Similarly, ACSL4 has been shown to be a key regulator of stroke, with inhibition of ACSL4 in vivo improving brain injury and neuroinflammation." (PMID 37372148, 2023). "The up-regulation of ACSL4 may facilitate or hinder neurological recovery after stroke through the regulation of ferroptosis." (PMID 36507355, 2022). "The baicalin, carthamin yellow, dauricine, (−)-epicatechin, kaempferol, and paeonol ameliorate neuronal ferroptosis in vitro or in vivo stroke models via regulating ACSL4, GPX4, TFR1, Fe2+, and NRF2 pathways, which show great potential in the treatment of stroke." (PMID 35264947, 2021). "Thus in the future, more studies should be done to reveal the specific mechanism concerning the role of ACSL4 in stroke." (PMID 34149358, 2021). "Furthermore, ACSL4 is an important target of ferroptosis, and the inhibition of ACSL4 promotes neurological recovery after stroke by regulating ferroptosis." (PMID 33889074, 2021). "We also wanted to review whether ACSL4 had the same effect on the accumulation of lipid ROS in ferroptosis after stroke." (PMID 33889074, 2021).
Stroke (continued). "The use of rosiglitazone to inhibit ACSL4 could significantly improve neurological function and reduce the brain infarct volume at 72 h after stroke." (PMID 33889074, 2021). "Furthermore, ACSL4-mediated esterification of PUFAs into peroxidation-vulnerable membrane domains establishes a self-reinforcing pathway, with elevated ACSL4 expression in stroke, AD, and PD intensifying lipid oxidative damage, collectively forming an iron-dependent oxidative injury axis." (PMID 40766185, 2025). "Further investigation into its mechanism reveals that Melatonin modulates ACSL4 ubiquitination and influences ferroptosis by boosting MDM2 expression, thereby leading to its therapeutic efficacy in treating stroke." (PMID 38289595, 2024). "ACSL4 induces PUFA esterification into phospholipids, thus promoting neuronal death by ferroptosis during stroke injuries." (PMID 37480159, 2023). "However, whether ACSL4 has a role in ferroptosis after stroke is still unclear." (PMID 33889074, 2021). "Our meta‐analysis supports these mechanisms, suggesting that acupuncture reduces ROS production in post‐stroke brain tissue, downregulates MDA and ACSL4 levels, inhibits lipid peroxidation, and may interrupt key ferroptosis pathways." (PMID 40842100, 2025).
gastric cancer (19 papers, 2020 to 2025). A primary or metastatic malignant neoplasm involving the stomach. "LncCBSLR decreased CBS levels to promote ACSL4 ubiquitination and degradation, thus protecting gastric cancer cells from ferroptosis." (PMID 37686142, 2023). "Decreased CBS results in reduced methylation of the ACSL4 protein and facilitates polyubiquitination and degradation of ACSL4 via the ubiquitination-proteasome pathway, ultimately protecting gastric cancer against ferroptosis." (PMID 37497000, 2023). "As an example, ACSL4 is significantly down-regulated in gastric cancer compared with cancer-adjacent normal gastric mucosa." (PMID 32286604, 2020). "However, the expression of ACSL4 is frequently down-regulated in gastric cancer, increasing cell growth and cell migration, and further studies are needed to explain these differences." (PMID 38370339, 2024). "In contrast, ACSL4 plays a tumor-suppressive role in gastric cancer and was thus frequently downregulated, and forced ACSL4 overexpression in gastric cancer cells impaired cell growth and migration, which is similar to what we have observed in lung adenocarcinoma cells." (PMID 34053456, 2021). "Moreover, transient overexpression of recombinant ACSL4 in gastric cancer cell lines significantly inhibited cell growth, proliferation and migration in vitro, whereas knockdown of ACSL4 induced reciprocal effects." (PMID 32286604, 2020). "The downregulation of CBS expression inhibits ferroptosis in gastric cancer (GC) cells by promoting the degradation of ACSL4." (PMID 40271153, 2025). "Interestingly, our results were similar to the studies of ACSL4 in gastric cancer tissues." (PMID 34053456, 2021). "ACSL4 inhibits cell proliferation and migration through the downregulation of focal adhesion kinase FAK and the upregulation of p21 expressions in gastric cancer." (PMID 40050614, 2025). "In the present study, CIRT significantly increased intracellular iron and ROS levels, upregulated ACSL4 expression, and downregulated GPX4 expression in gastric cancer cells." (PMID 40917841, 2025). "In gastric cancer, YTHDF2 reduces the stability of cystathionine β-synthase (CBS) mRNA, subsequently decreases the methylation of ACSL4, an important enzyme in lipid metabolism, and results in ACSL4 degradation and chemoresistance." (PMID 37055798, 2023). "Polyunsaturated fatty acid biosynthesis modulates gastric cancer cell ferroptosis, which is blocked by α6β4/SRC/STAT3-mediated inhibition of ACSL4 (acyl-coA synthetase long-chain family member 4)." (PMID 36289191, 2022). "Moreover, miR-221-3p was reported to target ATF3 to transcriptionally induce the expression of GPX4 and HRD1 and then promote the ubiquitination and degradation of ACSL4 by HRD1, resulting in ferroptosis suppression in gastric cancer cells." (PMID 37686142, 2023).